TNFRSF1A (TNF receptor superfamily member 1A)
Diseases named in the same sentence as TNFRSF1A in open-access papers (continued):
Sharing a sentence is not in itself a finding about the gene and the disease.
retinoblastoma (1 paper, 2019). A malignant tumor that originates in the nuclear layer of the retina. "FASLG, TNF, TNFRSF9, and TNFRSF1A, genes involved in FAS and TNF pathways, were expressed at significantly higher levels in Y79 retinoblastoma cells treated with magnetic hyperthermia compared to untreated cells." (PMID 31602343, 2019).
scleritis (1 paper, 2020). Inflammation of the sclera. "The TNFRSF1A haplotype was not significantly correlated with scleritis or its subgroups." (PMID 33287909, 2020).
skin papilloma (1 paper, 2022). A benign papillary neoplastic growth on the skin composed of epithelial cells and a fibrous stalk. "Chemical carcinogens, e.g., 7,12-dimethylbenz[a]anthracene and 12-0-tetradecanoylphorbol 13-acetate, induce H-ras-mutant skin papilloma and SCC, but deletion of the Tnfrsf1a mouse gene encoding TNFR1 dampens chemical carcinogen-induced skin and liver carcinogenesis." (PMID 36270982, 2022).
Stargardt disease (1 paper, 2024). "The discrepancy for reporting in favor of ABC was even greater for the periodic fever-associated TNFRSF1A(NM_001065.4) c.362G > A, p.(Arg121Gln) variant (81% vs 64%) and the Stargardt disease-associated ABCA4 Arg1868Ile variant (86% vs 67%)." (PMID 38778080, 2024).
tumor (403 papers, 1994 to 2026). "Independent predictors of higher risk of CWL included oropharyngeal location of the tumor (OR = 8.23; p = 0.0001) and TT genotype of TNFRSF1A gene (OR = 9.40, p = 0.0072)." (PMID 35884467, 2022). "Patients with TNFRSF1A variants (n = 8; 100%) also showed significant more often skin rashes compared to patients with MEFV variants (n = 4; 21%, p = 0.0074)." (PMID 32563262, 2020). "While TNFα or TNFR1,2/TNFRSF1A,1B targeting induce tumor development resistance, TRAIL/TNFSF10 deficiency accelerates hematological malignancies." (PMID 19759901, 2009). "Interestingly, the tumor location in the larynx and GG genotype of the TNFRSF1A gene were found to be significantly related to a lower risk of CWL (OR = 0.09; p = 0.0001, OR = 0.26; p = 0.0298, respectively)." (PMID 35884467, 2022). "Thus, we may conclude that CTHRC1 may induce tumor associated macrophage infiltration though GRN/TNFRSF1A and AnxA1/FPR1 pathways." (PMID 35928443, 2022). "In almost all cases we observed demethylation effect in the CpG islands of tumor tissues with one exception: the CpG island with coordinates chr13:-25,212,380–25,212,623, which could be associated with promoter region of the pseudogene TNFRSF1A." (PMID 32451390, 2020). "Consistent with previous reports, we found enrichment of sgRNA targeting genes associated with both IFN-gamma signalling (Jak1, Jak2, Ifngr2) and TNF signalling (Tnfrsf1a, Fadd) in tumour cells resistant to CAR-T cell killing." (PMID 39261596, 2024). "As a result of this study, we evaluated the expression of the splice variants of TNFRSF1A and TNFRSF1B receptor-encoding genes for TNFα on tumor cell lines of different origins in intact and TNFα-stimulated cultures." (PMID 37239433, 2023). "Immune infiltration analysis revealed a significant difference in the proportion of immune cells in tumor and normal tissue, and the expression levels of C1R, CCL2, and TNFRSF1A were associated with immune cell infiltration of GBM." (PMID 35726234, 2022). "To investigate this, we used CRISPR/Cas9 to delete Tnfrsf1a, encoding the TNF binding receptor, TNFR1, in MC38-OVA tumor cells." (PMID 35874669, 2022). "We found CAFs which highly expressed CTHRC1 (from F04 and F08) and tumor associated macrophages were mediated by a different set of ligand-receptor pairs, including THY1/aXb2 complex, GRN/TNFRSF1A, CD99/PILRA, CD74/MIF, APP/CD74, ANXA1/FPR1, etc." (PMID 35928443, 2022). "TNFRSF1A is a tumor necrosis factor receptor, and the interaction between tumor necrosis factor and TNFRSF1A plays an important role in inhibiting the occurrence of inflammation, tumor proliferation, migration, and invasion." (PMID 34504502, 2021). "TNFR1, also known as tumor necrosis factor receptor superfamily, member 1A (TNFRSF1A) or CD120a, is expressed on almost all host cells including various tumor cell types and tumor-associated endothelial cells." (PMID 34445397, 2021). "Several recent studies have shown that STAT3 transcriptionally regulates key tumor-driving genes that are essential for tumor pathogenesis, such as TNFRSF1A, MCY and SOX1." (PMID 31747963, 2019). "TGFβ and TNFRsf1a displayed high expression in both tumor cell compartments, while IL-4 and IFNγ had low expression levels." (PMID 20525400, 2010). "Additionally, TNFRSF1A plays crucial roles in tumor cell proliferation, invasion and metastasis." (PMID 40870378, 2025). "Additionally, CTHRC1 overexpression induced tumor associated macrophage infiltration via AnxA1/FPR1 and GRN/TNFRSF1A signaling pathway, indicating CTHRC1 might be a promising predictive factor for immunotherapy." (PMID 37404760, 2023). "In addition, the expression of key genes in the TNF-α/NF-κB signaling, including NFKB1 (p50), RelA (p65), TNFRSF1A (TNFR1), TNFR1-associated death domain protein (TRADD), and TNF receptor-associated factor 2 (TRAF2), was examined in the cell lines and tumor tissues of EBV-associated cancers." (PMID 35008199, 2021).
tumor (continued). "TNFRSF1A, one of the receptors for TNF-alpha, supports tumor development by activating NF-kappaB and regulating inflammation." (PMID 40870378, 2025). "We nominate CEBPD and TNFRSF1A/ITGB1 as actionable nodes and identify ARRDC3 as a spatially restricted effector with context-dependent tumor-modulatory functions warranting therapeutic exploration." (PMID 41235227, 2025). "RNA levels and protein activity of CD44, TNF Receptor Superfamily Member 1A (TNFRSF1A), and ANXA1 were elevated in these high NRF2 tumor cells." (PMID 40583858, 2025). "Many of these genes are well known, e.g., TNFRSF1A (TNFR1) or TGFBR2 which can be used against T cells to block apoptosis signaling or tumor suppressor signaling." (PMID 38459554, 2024). "Top gene hits identified through both screens involved in for example TNFα signaling were CFLAR, MAPK1, RIPK1, TNFRSF1A, and ICAM1, highlighting their role in regulating tumor sensitivity to TNF-α-induced cell death." (PMID 37732732, 2023). "PPAR-Riskscore was constructed by univariate Cox regression based on the expression of 4 genes (NR1D1, ILK, TNFRSF1A, and REN) in tumor tissues." (PMID 35481240, 2022). "TNF-α is a cytokine that binds to TNFRSF1A/TNFR1 and TNFRSF1B/TNFBR, is secreted by macrophages and induces tumor cell death and other inflammatory mediators and proteases that orchestrate inflammatory responses." (PMID 35453307, 2022). "NFKB1, NFKBIA, TNFRSF1A, and FASN were found to be related to DNA repair, which affects tumor sensitivity to DNA-damaging agents." (PMID 35899106, 2022). "Multiple mechanisms mediate Mφ activation and their co-stimulation of T cells to promote anti-tumor immunity, mainly through tumor necrosis factor (TNF) superfamilies of receptors (Tnfrsf1a/b) and CD4024,25." (PMID 34103524, 2021). "TNFRSF1A mediates STAT3 phosphorylation and promotes the accumulation of myeloid suppressor cells in the tumor microenvironment." (PMID 33028341, 2020). "The interaction of tumor necrosis factor-α (TNF-α) with its receptors: TNFRSF1A and TNFRSF1B is critical for the promotion of tumor growth, invasion and metastasis." (PMID 25010932, 2014). "Considering that CD44 and TNFRSF1A primarily function as receptors, while ANXA1 can participate in regulating the tumor immune microenvironment as a secreted protein, we focused on whether NRF2 regulates the tumor immune microenvironment through ANXA1." (PMID 40583858, 2025). "In the viral cytokine receptor pathway, upregulated genes (p = 1.39 × 10−5), including TNFRSF1A, CCL21, IL2RB, IL22RA1, and XCR1, suggest that oncolytic viruses exploit tumor-specific immune evasion mechanisms to selectively lyse tumor cells, activating anti-tumor immunity via DAMPs and PAMPs." (PMID 40406701, 2025). "Infliximab and adalimumab, two immune checkpoint inhibitors that could blockade TNF, TNFRSF1A, and TNFRSF1B, were also included in the network, further highlighting the potential utilities in tumor immunotherapy of TNBC." (PMID 36291687, 2022). "Lower levels of SIGIRR and of TOLLIP, NFRKB, TNFRSF1A, and CD14 and of two distinct MAP kinases were detected in all the cancer cell lines analyzed; on the contrary, IRAK1 and HSPD1 mRNAs were upregulated in all the tumor cells." (PMID 35814450, 2022). "Moreover, the communication between tumor and immune cells was more widespread in the HER2neg group, especially in immune response-related crosstalk between tumor cells and myeloid cells (which was primarily comprised of macrophages), such as “HLA-DPB1–TNFSF13B” and “TNFRSF1A–GRN”." (PMID 36998014, 2023). "TNFRSF1A and TNFRSF1B, as the TNF receptors, were highly expressed in epithelial-like and mesenchymal-like malignant cells, suggesting that the TNF signaling pathway may promote tumor metastasis by inducing the EMT process of tumor cells." (PMID 36291687, 2022). "This context-specific axis offers targeted opportunities, like TNFRSF1A or CEBPD inhibition, to block mesenchymal invasion without impacting core tumor pathways." (PMID 41235227, 2025).
cancer (255 papers, 2002 to 2026). A tumor composed of atypical neoplastic, often pleomorphic cells that invade other tissues. "The development of primary cancers and metastases were inhibited in TNFRSF1A-deficient mice." (PMID 31146704, 2019). "This process is achieved through the binding of TNFA to its receptor TNFRSF1A, which is generally highly expressed in cancer cells." (PMID 39114912, 2024). "We then tested which cancer gene perturbations showed TNFR1-dependent clonal expansion by comparing the expansion rates in wild-type versus Tnfrsf1a+/− P60 skin." (PMID 39020166, 2024). "TCGA human cancer database analysis revealed that increased TNFRSF1A is correlated with significantly reduced survival of lung ADC patients." (PMID 37686574, 2023). "CDKN2A displayed higher mutation rates across multiple cancer types (31%), and other frequently mutated genes included LRPPRC (13%), PRKAA2 (11%), VLDLR (9%), ASNS (8%), GZMA (7%), GLS (7%), TNFRSF1A (6%), PSAT1 (5%), and PRDX6 (4%)." (PMID 37534256, 2023). "Tumor necrosis factor receptor 1 (TNFR1), encoded by TNFRSF1A, is a critical transducer of inflammatory pathways, but its physiological role in human cancer is not completely understood." (PMID 36270982, 2022). "Cancer development and progression was seen to be affected by Tnfrsf1a, Adrbk2, Pld4, Gnat1 and Samsn1 in other studies." (PMID 34185104, 2021). "Genetic polymorphisms of tumor necrosis factor (TNF) -α and its surface receptors, TNFRSF1A and TNFRSF1B have been examined in terms of susceptibility to various cancers." (PMID 20646319, 2010). "More recently, given that cancer progression is preceded by a long period of subclinical inflammation, the genetic polymorphisms of TNF-α, TNFRSF1A and TNFRSF1B have been examined in terms of susceptibility to various cancers." (PMID 20646319, 2010). "To experimentally test whether the TNF pathway directly mediates clonal expansion in phenotypically normal epithelia, we crossed Cas9 mice with Tnfrsf1a+/− mice and used ultrasound-guided in utero microinjection to target the 150 cancer genes in E9.5 embryos." (PMID 39020166, 2024). "Likewise, TNFRSF1A and pathways in cancer were majorly targeted/modulated protein and pathways respectively." (PMID 32772313, 2020). "Our result identified the FADD, TNFRSF1A, CASP9, MLKL, and CASP4 involved in the PANoptosis process and significantly affect patient survival, which can provide future direction in cancer research." (PMID 36874021, 2023). "Gene ontology analysis also indicated that IFNG, TNFRSF1A and CD3 are involved in the positive regulation of tyrosine phosphorylation of STAT proteins, which are known to be involved in cancer and inflammation." (PMID 35745107, 2022). "The bubble map indicated that the receptor TNFRSF1A and its corresponding ligand GRN played an important role in the communication between myofibroblasts and basal cells or cancer stem cells." (PMID 35620271, 2022). "All the down-regulated genes, in this Panel 3 showed their significant up-regulation in most of many types of cancers (TGM2, CSNK1A1, CTNNA1, NAMPT/Visfatin, TNFRSF1A, ETS1, SRC-1, FN1, APLP2, DMBT1/SAG, AIB1, AZIN1)." (PMID 23122428, 2012). "Of these genes, TNFRSF1A and TRADD were found to be upregulated since they work as the trigger molecules of the apoptotic cascade in cancer cells whereas antiapoptotic genes MCL-1 and LTBR were found to be downregulated." (PMID 20673323, 2010). "Moreover, we unveil a negative crosstalk between ETV7 and STAT3 in the regulation of the TNFRSF1A gene, and this crosstalk highlights the importance of ETV7 in cancer immunity and inflammation." (PMID 37041130, 2023). "Additionally, the average expression of TNF-related genes, including TNFRSF1A, TNFRSF1B, TNFSF10, and TNFRSF21, was higher than that of most other necroptosis genes in pan-cancer." (PMID 37000317, 2023).
infection (171 papers, 2006 to 2026). The state of being infected such as from the introduction of a foreign agent such as serum, vaccine, antigenic substance or organism. "Since TNF-α signaling is key in both the acute infection and CCC, we added TNFA and TNF-receptor alpha (TNFRSF1A) to this table, even though TNFA was only assessed in association studies (120–123, 132, 133, ), and TNFRSF1A only in knockout infection experiments." (PMID 30559742, 2018). "There are also immunity pathways enriched in the DEGs of GCs, like the regulation of tumor necrosis factor receptor 1 (TNFRSF1A) and infection response." (PMID 37880448, 2023). "Transcriptomics results showed that Tnfrsf1a encoding TNF-α receptors were upregulated in the liver and spleen of mice in the Pair group after infection, suggesting that the expression level of the receptors can also affect the immune response." (PMID 34489943, 2021). "Accordingly, we also investigated the response of double-null Tnfrsf1a/1b−/− mice to infection with SARS-CoV." (PMID 27663205, 2016). "Four days after infection, the genes of chemokine receptors CCR2 and of TNF receptor 1 (TNFRSF1A) both involved in cell recruitment and orchestration of pro-inflammatory immune responses, were more highly expressed in the SLT-LS group compared to SLT-SS." (PMID 40079593, 2025). "Three death receptors (TNFRSF1A, FAS, and TNFRSF10) were expressed at higher levels after mutant infection." (PMID 37513744, 2023). "Some of these genes belong to the NF-kappa B (NF-κB) (PLAU, VCAM1, TNFRSF1A) and/or mitogen-activated protein kinase (MAPK) (TNFRSF1A and PGF) signaling pathways, indicating a differential regulation of the inflammatory response in lungs for both infection outcomes." (PMID 35003125, 2021). "In contrast, transcript expression of the TNF-α receptors TNFR1 (Tnfrsf1a) and TNFR2 (Tnfrsf1b) were not altered in the brain following infection, suggesting that enhanced TNF-α signaling in this setting is mediated primarily through induction of cytokine expression." (PMID 35462541, 2022). "Many genes associated with the cell death such as tumour necrosis factor receptor (Tnfrsf1a), inhibitor of kappaB kinase (Ikbkg), kinases (Cd82 and Cdk2), and apoptosis regulator (Bcl2l1 and Birc2) were only up-regulated in WT infection and showed no expression in BM16 infection." (PMID 27634329, 2016).
bacterial infection (19 papers, 2009 to 2025). "None of the SNPs in IRGM, ATG16L1 and TNFRSF1A gene was found to be significantly associated with susceptibility to bacterial infection." (PMID 34407136, 2021).
inflammation (16 papers, 2013 to 2025). Aberrant reaction of the microcirculation characterized by movement of fluid and leukocytes from the blood into extravascular tissues. "Consistent with worsened renal dysfunction, Ang II infusion in the ApoEKO mice exhibited exacerbation of kidney inflammation with enhanced expression of TNF-α, TNFRSF1A, IL-1β, IL-6, and IL-17A." (PMID 26245758, 2015).
neurological diseases (9 papers, 2014 to 2025). "TNFRSF1A gene encodes TNFR1, a major mediator of TNF-α signaling, crucial in inflammation, apoptosis, and immune response, and is linked to various disorders, especially autoinflammatory and neurological diseases." (PMID 40520613, 2025).
immune diseases (6 papers, 2014 to 2025). "Among those, six gene knockouts resulted in an immune disease, including Cd28, Ndfip1, Skap2, Tmem258, Tnfrsf1a, and Tnfrsf9." (PMID 35591976, 2022). "The colocalization of several TNF receptor superfamily members (TNFRSF1A, TNFRSF9, and TNFRSF14) further supports the development of drugs modulating TNF pathway, one of the main therapy lines for treating immune diseases." (PMID 35591976, 2022).
autosomal dominant disease (3 papers, 2011 to 2021). Autosomal dominant form of disease. "TRAPS is an autosomal dominant disease caused by a mutation in the TNFRSF1A gene encoding tumor necrosis factor receptor 1 (TNF-R1)." (PMID 33603750, 2020). "Tumor necrosis factor receptor–associated periodic syndrome (TRAPS) is an autosomal-dominant disease caused by mutations of the type I tumor necrosis factor receptor (TNFRI) gene (TNFRSF1A)." (PMID 21225694, 2011). "TRAPS is an autosomal dominant disease, caused by mutations in TNFRSF1A gene which encodes the protein named tumor necrosis factor receptor 1 (TNFR1), which plays a crucial role in the inflammation and apoptosis." (PMID 33530412, 2021).
lung (3 papers, 2022 to 2023). "In addition, patients with lung SCCs expressing high levels of TNFRSF1A and REL died earlier than patients with lung SCC expressing low levels of these genes." (PMID 37686574, 2023). "Moreover, we compared TNFRSF1A genomic alterations in three human lung SCC and three human lung ADC cohorts and found that TNFRSF1A amplification was a major type of genomic alteration in the SCC cohorts compared to ADC." (PMID 36270982, 2022).
metabolic disorder (3 papers, 2019 to 2025). "Hence, by virtue of their efficient Tnfrsf1a targeting capacity, synthetic 2′-O-methylated miR156c and miR159a mimics may represent valuable therapeutics to reduce inflammation at least in the metabolic diseases associated with adipocyte dysfunction." (PMID 31453381, 2019).
blood cancers (1 paper, 2019). "In FVPTC samples, LGALS3, an IA gene, is strongly associated with genes associated with blood cancers (RUNX1, BCL2L1, CBFB, and TNFRSF1A), suggesting a strong immune association in LGALS3 activity." (PMID 31443155, 2019).
respiratory diseases (1 paper, 2024). "Next, complementary analyses identified nine DMGs (LTA, STAT3, IKBKG, IRAK1, NOD2, TLR2, TNFRSF1A, and IKBKB) that might be involved in the immune response of XJB cattle infected with respiratory diseases." (PMID 38732144, 2024).
TNFRSF1A also shares sentences with these, for which no sentence is quoted: colitis (40 papers); melanoma (31); kidney disease (28); inflammatory bowel disease (25); neurodegenerative disease (23); diabetic kidney disease (21); Cognitive impairment (20); colorectal cancer (20); end-stage renal disease (20); Hypertension (19); Autoimmunity (18); Alzheimer disease (17); colon carcinoma (16); Hepatic steatosis (13); hepatocellular carcinoma (13); Hepatitis (11); Hyperammonemia (11); myocardial infarction (11); osteoarthritis (11); cardiovascular disease (10); steatosis (10); tuberculosis (10); cognitive decline (9); endothelial dysfunction (9); injury (9); Cerebral ischemia (8); dementia (8); endometriosis (8); type 1 diabetes (8); acute GVHD (7).
A further 375 diseases each share a sentence with TNFRSF1A in 7 papers or fewer.